MED29 (mediator complex subunit 29)
Description:
Component of the Mediator complex, a coactivator involved in the regulated transcription of nearly all RNA polymerase II-dependent genes. Mediator functions as a bridge to convey information from gene-specific regulatory proteins to the basal RNA polymerase II transcription machinery. Mediator is recruited to promoters by direct interactions with regulatory proteins and serves as a scaffold for the assembly of a functional preinitiation complex with RNA polymerase II and the general transcription factors.
Synonyms: IXL; DKFZp434H247; MED2
Tractability: Small molecule: a structure with a bound ligand is known. PROTAC: ubiquitination databases record sites on it.
Gene: Protein-coding gene on chromosome 19 (39,391,303 to 39,400,641, forward strand). Ensembl gene ENSG00000063322.
Subcellular location: Nucleus
Subcellular location (Human Protein Atlas): Nucleoplasm
Pathways (Reactome):
Developmental Biology: Transcriptional regulation of white adipocyte differentiation
Disease: RSV-host interactions
Metabolism: PPARA activates gene expression
Gene Ontology:
Molecular function: protein binding; transcription coregulator activity
Biological process: positive regulation of transcription elongation by RNA polymerase II; positive regulation of transcription initiation by RNA polymerase II; regulation of transcription by RNA polymerase II; RNA polymerase II preinitiation complex assembly
Cellular component: core mediator complex; mediator complex; nucleoplasm; nucleus
Genetic constraint (gnomAD): Loss-of-function variants: 14 observed, 21.96 expected, observed/expected ratio (o/e) 0.64, 90% interval 0.42 to 1. The upper end of that interval is the gene's LOEUF score, 1, which puts it in group 4 of 6, group 1 being the genes least tolerant of losing a copy. Missense variants: 241 observed, 260.91 expected, observed/expected ratio (o/e) 0.92, 90% interval 0.83 to 1.03. Synonymous variants: 123 observed, 112.02 expected, observed/expected ratio (o/e) 1.1, 90% interval 0.95 to 1.27.
Homologues: Orthologues: macaque MED29 (100% identical), chimpanzee MED29 (99% identical), dog MED29 (98% identical), guinea pig MED29 (96% identical), mouse Med29 (92% identical), rabbit MED29 (62% identical).
Diseases named in the same sentence as MED29 in open-access papers:
MED29 is named in the same sentence as 14 diseases in open-access papers, as found by Europe PMC text mining. Sharing a sentence is not in itself a finding about the gene and the disease. The quoted sentences say what the papers report.
non-small cell lung carcinoma (5 papers, 2023 to 2026). A group of at least three distinct histological types of lung cancer, including non-small cell squamous cell carcinoma, adenocarcinoma, and large cell carcinoma. "AS-TDR-007333 activates MED29 to further promote malignant transformation of non-small cell lung cancer cells through two different mechanisms." (PMID 38443680, 2024). "In non-small cell lung cancer (NSCLC), AS-tDR-007333 is a novel oncogenic tRF that activates mediator of RNA polymerase II transcription subunit 29 (MED29) through two distinct mechanisms to promote NSCLC cell malignancy." (PMID 41550494, 2026). "In our previous work, we found that As-tDR-007333 promoted non-small cell lung cancer (NSCLC) malignancy through regulating H3K4me1 and H3K27ac modifications and augmenting ELK4-mediated MED29 transcription." (PMID 39039568, 2024). "AS-tDR-007333 enhances non-small cell lung cancer cell proliferation and migration via the HSPB1/MED29 and ELK4/MED29 axes." (PMID 36818350, 2023).
pancreatic cancer (4 papers, 2015 to 2024). "In pancreatic cancer, MED29 regulates migration and invasion through the ERK1/2 pathway, exerting a pro-carcinogenic effect." (PMID 39462350, 2024). "There was only one report showing that MED29 was overexpressed in pancreatic cancer and promoted pancreatic cancer cell viability." (PMID 35526007, 2022). "For example, the CDK8 kinase module and MED29 promoted the expression of β-catenin in colorectal cancer, and they were shown to have oncogenic and tumor-suppressive functions, respectively, in pancreatic cancer cells." (PMID 34649520, 2021).
microcephaly (1 paper, 2025). A congenital or acquired developmental disorder in which the circumference of the head is smaller than normal for the person's age and sex. "ShRNA-mediated knockdown of MED29 in mouse hippocampal cultures significantly reduced neurite length and dendritic arborization, likely consistent with the severe microcephaly of the patients." (PMID 40745490, 2025).
oral cancer (1 paper, 2024). "In the co-transfected group, migration was between the CHRDL1 overexpression group and the MED29 group, suggesting that MED29 can reverse the inhibitory effect of CHRDL1 on oral cancer migration, indicating that CHRDL1 plays a regulatory role in the CHRDL1-MED29 signaling axis." (PMID 39462350, 2024).
tumor (5 papers, 2015 to 2025). "Aberrant activation of the MAPK pathway is often associated with malignant phenotypes in tumor cells, while overexpression or knockdown of MED29 has been shown to affect the behavior of tumor cells." (PMID 39462350, 2024). "Interestingly, AS-tDR-007333-inhibitor also suppressed the expressions level of MED29 protein in xenograft tumor, suggesting that the tumor suppression function of AS-tDR-007333-inhibitor was associated with down-regulation of MED29 expression." (PMID 35526007, 2022). "Studies suggest that the expression level of MED29 is closely associated with clinical pathological characteristics of tumors, such as tumor size, staging, lymph node metastasis, and distant metastasis, further demonstrating its crucial role in tumor development." (PMID 39462350, 2024). "The analysis revealed that in OSCC tissues, the expression of MED29 was significantly decreased compared to the control tumor tissues." (PMID 39462350, 2024). "MED29 expression was elevated in tumor tissues of OSCC patients compared with adjacent cancer tissues." (PMID 39462350, 2024). "Although direct evidence may be limited, theoretically, the interaction or mutual regulation between the MAPK signaling pathway and MED29 may hold significant importance in the behavior of tumor cells." (PMID 39462350, 2024). "Interestingly, the expression levels of AS-tDR-007333 were positively correlated that of MED29 in NSCLC tumor tissues." (PMID 35526007, 2022). "Furthermore, the expression levels of AS-tDR-007333, HSPB1, ELK4, and MED29 in xenograft tumor tissues were significantly suppressed in the AS-tDR-007333-inhibitor group compared with that of NC and control groups." (PMID 35526007, 2022). "Furthermore, the expression levels of MED29 in NSCLC tumor tissues were significantly higher than that in the adjacent tissues." (PMID 35526007, 2022).
cancer (3 papers, 2010 to 2024). A tumor composed of atypical neoplastic, often pleomorphic cells that invade other tissues. "While studies have indicated that loss of MED29 function leads to reduced mRNA levels and subsequently decreased Pol II transcriptional gene expression, its role in cancer remains unclear." (PMID 39462350, 2024). "Studies have indicated that MED29 is a subunit gene carrying more structural chromosomal abnormalities and is overexpressed in various malignant tumors." (PMID 39462350, 2024). "While studies have showed that loss of MED function resulted in decreased mRNA levels and concomitant diminished expression of Pol II transcribed genes, relatively little is known about the role of MED29 in cancers." (PMID 35526007, 2022).
infection (2 papers, 2020 to 2024). The state of being infected such as from the introduction of a foreign agent such as serum, vaccine, antigenic substance or organism. "Unexpectedly, distinct subunits appear to be involved in the response to this type of infection, in which the pathogen breaks through the cuticle, namely Med27 and possibly Med7 and Med29." (PMID 33746938, 2020). "Experimental results indicate that in CAL27 and SCC25 cell lines, infection with lentivirus overexpressing MED29 significantly increased the levels of MED29 mRNA, confirming the successful construction of the MED29 overexpression cell models and laying the foundation for further research." (PMID 39462350, 2024).
neurodegenerative disease (1 paper, 2025). A disorder of the central nervous system characterized by gradual and progressive loss of neural tissue and neurologic function. "In conclusion, we demonstrate that MED29 is a novel disease-causing gene of a severe neurodegenerative disease with a distinct phenotype including PCH and cataract." (PMID 40745490, 2025).
MED29 also shares sentences with these, for which no sentence is quoted: colorectal cancer (2 papers); breast fibroepithelial tumors (1); cataract (1); lung carcinoma (1); prostate carcinoma (1); Uterine leiomyoma (1).